NOX4 (NADPH oxidase 4)
Diseases named in the same sentence as NOX4 in open-access papers (continued):
Sharing a sentence is not in itself a finding about the gene and the disease.
silicosis (2 papers, 2019 to 2020). Silicosis is a respiratory disease caused by breathing in (inhaling) silica dust. "Results demonstrated an elevated expression of key components of Wnt/β-catenin signaling and NOX4 in the lungs of silicon dioxide- (SiO2-) induced silicosis mice." (PMID 33376577, 2020). "The in vivo results demonstrated an enhanced activity of Wnt/β-catenin and NOX4 signaling in SiO2-induced mouse silicosis lungs." (PMID 33376577, 2020). "The results demonstrated that both Wnt/β-catenin and NOX4 signaling were elevated in the lungs of SiO2-induced silicosis mice." (PMID 33376577, 2020). "Moreover, the increased abundances of Wnt3a, NOX4, α-SMA, and vimentin were further corroborated to be predominantly expressed in the silicosis nodules of silica-challenged lungs as determined by the immunofluorescent staining (IF) assay." (PMID 33376577, 2020). "However, the link between Wnt/β-catenin signaling and NOX4-mediated ROS in the development of silicosis has not been established." (PMID 33376577, 2020).
small cell lung carcinoma (2 papers, 2017 to 2021). Small cell lung cancer (SCLC) is a highly aggressive malignant neoplasm, accounting for 10-15% of lung cancer cases, characterized byrapid growth, and early metastasis. "Among the three identified TME-based prognostic genes (LPPR4, ADAM12, NOX4), ADAM12, which was found to be overexpressed in small cell lung cancer patients, has been proven to be a potential prognostic biomarker for cancer." (PMID 35178071, 2021).
squamous carcinoma (2 papers, 2014 to 2017). "Immnohistochemical analysis showed that NOX4 was highly expressed in about 82% of NSCLC samples (125 of 152) both of adenocarcinoma and squamous carcinoma, whereas the adjacent normal tissues of NSCLC had much lower levels of NOX4 expression." (PMID 24946933, 2014). "Statistical analyses revealed that NOX4 expression was strongly correlated with the clinical stage and tumor-nodule-metastasis (TNM) classification in NSCLC patients both of adenocarcinoma and squamous carcinoma." (PMID 24946933, 2014).
steatosis (2 papers, 2023 to 2025). Increased lipid within the cytoplasm of cells. "To test this, we isolated hepatocytes from control (Nox4fl/fl) and hepatocyte-specific NOX4-deficient mice (Alb-Cre Nox4fl/fl) fed a HFD for 10 weeks to induce steatosis and assessed H2O2 levels and the expression of NFE2L2 and its target genes." (PMID 38060313, 2023). "Our studies demonstrate that, whereas steatosis and resultant increases in mitochondrial ROS drove NOX4 expression in NAFL, the progression toward more advanced disease with fibrosis was accompanied by reduced NOX4 and concomitantly reduced antioxidant defense." (PMID 38060313, 2023). "Interestingly, the deletion of Nox4 in hepatocytes also increased DIO and enhanced steatosis, which is a risk factor for the progression to NASH." (PMID 38060313, 2023). "Importantly, we found that NOX4 overexpression in hepatocytes was able to increase antioxidant defense and decrease steatosis, inflammation, and fibrosis in mice fed a NASH- and fibrosis-promoting CD-HFD." (PMID 38060313, 2023). "Thus, the deletion of NOX4 in the liver not only promoted steatosis but also facilitated the transition to NASH and ensuing fibrosis in DIO." (PMID 38060313, 2023). "Therefore, the deletion of hepatocyte Nox4 in adult obese mice could abrogate the antioxidant defense response otherwise induced during NAFL to exacerbate steatosis and facilitate the transition to NASH and fibrosis." (PMID 38060313, 2023). "Moreover, sUA stimulates the production of reactive oxygen species by activating NADPH oxidases, particularly NOX4, leading to aberrant activation of NLRP3, which contributes to hepatic steatosis and inflammation." (PMID 40089555, 2025). "Next, we sought to determine whether NOX4 deletion might be sufficient to drive NASH and fibrosis in adult mice that were already obese and had established steatosis." (PMID 38060313, 2023). "Therefore, the deletion of NOX4 in hepatocytes exacerbated DIO and promoted steatosis that was attributable, at least in part, to increased de novo lipogenesis." (PMID 38060313, 2023).
subarachnoid hemorrhage (2 papers, 2019 to 2020). A serious neurological disorder characterized by intracranial hemorrhage into the subarachnoid space. "Expressed highly in brain astrocytes, NOX4 has been associated with subarachnoid hemorrhage-induced oxidative stress." (PMID 32316287, 2020). "This is consistent with recent findings that NOX2 and NOX4 mRNA silencing improved neuronal survivability by preventing apoptosis in a subarachnoid hemorrhage model." (PMID 30777083, 2019).
Ventricular arrhythmia (2 papers, 2022 to 2025). "Ageing accelerates cardiac remodelling and increases the susceptibility to ventricular arrhythmias through NOX4/ROS/CaMKII pathway-mediated abnormal membrane voltage and intracellular Ca2+ handling and Vm/Ca2+ coupling." (PMID 35387264, 2022). "Increased levels of mitochondrial NOX4 during aging lead to a higher inducibility of self-limiting ventricular arrhythmias." (PMID 40564184, 2025). "Taken together, NOX4/ROS-activated CaMKII may contribute to increased ventricular arrhythmias by inducing abnormal Ca2+ handling in elderly hearts." (PMID 35387264, 2022).
acanthamoebiasis (1 paper, 2023). "The aim of the study was to analyze the gene expression and protein concentration of NADPH oxidase 2 and 4 (NOX2 and NOX4, respectively) and nuclear erythroid 2-related factor (Nrf2) in the kidneys of hosts with systemic acanthamoebiasis." (PMID 38041167, 2023).
adenoma (1 paper, 2021). A neoplasm arising from the epithelium. "Additionally, the expression level of NADPH oxidase 4 (NOX4) significantly increased, while that of hemoxygenase-1 (HO-1) and nuclear factor erythroid 2-related factor 2 (Nrf2) significantly decreased in PRAT of patients with cortisol-producing adenoma." (PMID 34408726, 2021).
age (1 paper, 2020). A temporal measurement of the time period elapsed since an identifiable point in the life cycle of an organism. "Therefore, the upregulation of NOX4 and p16 indicated more senescent NP cells in age-related degenerative discs." (PMID 32025238, 2020).
Age-related cataract (1 paper, 2020). A type of cataract (opacification of the lens) that forms during the course of aging. "We concluded that miR-182-5p inhibited lens epithelial cells apoptosis through regulating NOX4 and p38 MAPK signaling, providing a novel biomarker for treatment of age-related cataract." (PMID 32552665, 2020).
alcoholic fatty liver disease (1 paper, 2015). Lipid infiltration of the hepatic parenchymal cells that is due to alcohol abuse. "We have no definitive explanation for the protective effect exerted by the A-allele of NOX4 rs3017887 regarding MS, especially because this same SNP did not influence the frequency of MS in patients with non-alcoholic fatty liver disease (data not shown)." (PMID 25888935, 2015).
allergic rhinitis (1 paper, 2016). Inflammation of the nasal mucous membranes caused by an IgE-mediated response to external allergens. "NOX-4, localized mainly in the epithelial layer, may play an important role in reactive oxygen species production, contributing to the oxidative stress in allergic rhinitis and nasal polyp tissues." (PMID 27212811, 2016).
alveolitis (1 paper, 2022). "However, there was less airway inflammatory cell infiltration, alveolitis and peribronchiolar inflammation and overall inflammation in the lungs of infected NOX4 TG mice, 3-days post infection." (PMID 35601109, 2022). "However, at 7-days post infection there was a significant increase in alveolitis, peribronchiolar inflammation and inflammatory cells in the lungs of both WT mice and NOX4 TG mice that were similar in magnitude." (PMID 35601109, 2022). "There was no significant increase in alveolitis, peribronchiolar inflammation and inflammatory cells in the lungs of infected NOX4 TG mice after three days compared to the infected NOX4 TG mice." (PMID 35601109, 2022).
arterial disease (1 paper, 2022). "Activation of a novel TGFβ/NOX4 axis in the endothelium was suggested to be responsible for eNOS uncoupling and arterial disease in Fbn1C1041G/+ mice." (PMID 35053276, 2022). "Inhibition and even reversion of arterial disease in Fbn1C1041G/+ mice by lentiviral mediated Prkg1 silencing greatly contrast the relatively modest attenuation of TAA pathology observed in Fbn1C1041G/+; Nox4−/− mice." (PMID 35053276, 2022).
carotid atherosclerosis (1 paper, 2022). A thickening and loss of elasticity of the walls of carotid arteries that occur with formation of atherosclerotic plaques. "Based on the results of bioinformatics analysis, we further identified 10 most critical ferroptosis-related genes in carotid atherosclerosis by PPI analysis including HMOX1, IL1B, and NOX4." (PMID 36393970, 2022).
cerebral artery occlusion (1 paper, 2021). "For example, Wang and colleagues demonstrated that exogenously supplied H2S significantly reduced cerebral NOX4 expression in a mouse model of middle cerebral artery occlusion." (PMID 34576259, 2021).
cerebrovascular disease (1 paper, 2020). "Ischemia/reperfusion injury induces upregulation of Nox4, which, as a key source of oxidative stress, offers a new therapeutic target in cerebrovascular disease." (PMID 32802129, 2020).
clear cell carcinoma (1 paper, 2012). "Clinically relevant is the fact that the AMPK activator, AICAR, which we show in this study to reduce Nox4 expression and IL-6 and IL-8 production, reduces RCC cell invasion in vitro and in ex vivo RCC cells isolated from a human clear cell carcinoma tumor." (PMID 22303451, 2012).
colorectal tumour (1 paper, 2023). "Inhibition of Reactive Oxygen Species‐producing enzyme NOX4 blocked the differentiation of CAFs, thereby promoting the infiltration of CD8+ T cells and ICI response in syngeneic murine lung tumour and colorectal tumour models." (PMID 38115703, 2023).
complication (1 paper, 2017). Any disease or disorder that occurs during the course of, or because of, another disease, treatment, or procedure. "GLP-1 ameliorated high-glucose-induced oxidative stress by inhibiting NOX4, p47phox, and Rac-1 expression and translocation of p47phox, suggesting its clinical usefulness in diabetic vascular complications." (PMID 28808291, 2017).
congestive heart failure (1 paper, 2017). Failure of the heart to pump a sufficient amount of blood to meet the needs of the body tissues, resulting in tissue congestion and edema. "In particular, NOX2 and NOX4 are both highly expressed in heart tissue, and contribute to ROS-related pathologies including tissue damage during congestive heart failure and cardiovascular disease, especially in aged tissue." (PMID 28423654, 2017).
Corneal opacity (1 paper, 2023). A reduction of corneal clarity. "In this study, we revealed that cryoinjury on the corneal endothelium of SD rats caused corneal opacity and reduced cell density, which was ameliorated by NOX4 inhibition." (PMID 37371958, 2023). "The in vivo transfection of siNOX4 and pNOX4 into the corneal endothelium of rats showed that NOX4 overexpression causes corneal opacity, and reduces cell density, despite no cryoinjury." (PMID 37371958, 2023).
coxarthrosis (1 paper, 2025). "This pilot study aimed to investigate the effects of a cocktail with trolox, r-irisin and resveratrol on the metabolism of osteoblasts isolated from patients with coxarthrosis or fragility fracture by assessing the modulation of NOX4, SIRT1 and PTX3." (PMID 40956314, 2025).
cystadenoma (1 paper, 2018). A benign or borderline cystic epithelial neoplasm arising from the glandular epithelium. "Analysis of the cystadenomas from these kidneys showed almost undetectable levels of tuberin with a concomitant increase in expression of Nox4." (PMID 29491408, 2018).
cystic kidney disease (1 paper, 2024). A congenital or acquired kidney disorder characterized by the presence of renal cysts. "NOX4 and xanthine oxidase inhibitors, mitochondrial antioxidants, dietary modifications, and tolvaptan are potential treatments addressing ROS in cystic kidney disease, yet there is limited randomized controlled trial research performed on humans demonstrating their efficacy and safety." (PMID 39456439, 2024).
diabetic vascular disorders (1 paper, 2019). "Also, catalpol regulates the levels of nitric oxide (NO), lactate dehydrogenase (LDH), 8-iso-prostaglandin F2α, p22phox, and NOX4 in diabetic vascular disorders." (PMID 31514313, 2019).
dysferlinopathy (1 paper, 2022). "NOX4-expressing PDGFRα+ cells were also found in the muscles of mice that model limb-girdle MD 2B (LGMD2B) (dysferlinopathy) and LGMD2F (δ-sarcoglycan deficiency); therefore, these observations are not restricted to dystrophin-deficient muscle." (PMID 36278481, 2022).
emphysema (1 paper, 2021). "In the present study, we found that the expression of NOX4 and α-SMA was markedly elevated in the small airway of COPD patients and CS-induced emphysema mice." (PMID 33824697, 2021). "Cigarette smoke- (CS-) induced emphysema mice were generated, and the alteration of α-SMA, NOX4, TGF-β1, and collagen I was accessed." (PMID 33824697, 2021). "Additionally, an increased abundance expression of NOX4 and α-SMA was observed in the lungs of the CS-induced emphysema mouse model." (PMID 33824697, 2021).
enteritis (1 paper, 2025). Inflammation of the small intestine. "The upregulation of NOX4 plays a significant role in the pathogenesis of enteritis." (PMID 40431496, 2025). "Among the members of the NOX family, NOX1, NOX2, and NOX4 are particularly relevant to enteritis." (PMID 40431496, 2025).
epilepsy (1 paper, 2023). A brain disorder characterized by episodes of abnormally increased neuronal discharge resulting in transient episodes of sensory or motor neurological dysfunction, or psychic dysfunction. "Therefore, we analyzed the NOX4 expression in human hippocampal brain sections obtained from epilepsy surgery." (PMID 37081190, 2023).
Era (1 paper, 2025). "The protein expression levels of NOX4 and mRNA expression levels of NOX1 and NOX2 in the Era-induced group were significantly upregulated compared to those in the NC group." (PMID 39754271, 2025). "The protein expression levels of OPN, sEH, and NOX4, as well as the mRNA expression levels of NOX1 and NOX2, in the Era-induced group were significantly upregulated compared to those in the NC group." (PMID 39754271, 2025).
fibroids (1 paper, 2023). "Furthermore, a novel medical treatment of fibroids could be to disrupt inflammatory signaling through the inhibition of NOX4 or leptin receptors." (PMID 37628676, 2023).
G6PD deficiency (1 paper, 2022). An X-linked genetic condition caused by alterations in the gene G6PD that result in moderately to severely decreased activity levels of the enzyme glucose-6-phosphate dehydrogenase. "G6PD deficiency in zebrafish impairs redox signaling mediated by NADPH oxidase-4 (NOX4) and down-regulates Smad3 and miR-200b, which are involved in embryonic stem cell differentiation and stability." (PMID 35216131, 2022).
gastric ulcer (1 paper, 2019). An ulcerated lesion in the mucosal surface of the stomach. "Interestingly, ethanol-induced gastric ulcer was associated with Nrf2 downregulation, which was correlated with NOX-1, 2 NOX-4, and HMGB1 upregulation, and was significantly reversed by RK pre-treatment." (PMID 31404064, 2019). "In the present study, the expression of NOX-1 and NOX-4 in gastric tissues was significantly higher in the ethanol positive ulcer group compared to the control group and thus might contribute to gastric ulcer pathogenesis." (PMID 31404064, 2019).
gastritis (1 paper, 2025). Inflammation of the stomach. "HIF1α, CEACAM6, and NOX4 upregulation was detected in gastritis and GC tissues." (PMID 40325849, 2025).
gestational diabetes (1 paper, 2025). Carbohydrate intolerance first diagnosed during pregnancy. "Detailed analysis of angiogenic function and signalling (Western blot, RNA sequencing) was performed in CB-ECFCs isolated from donors with gestational diabetes prior to NOX4 plasmid OE to define rescue potential and key mechanistic pathways (network analysis, proteome profiling)." (PMID 40457435, 2025). "IPA of our RNA sequencing dataset generated from CB-ECFCs isolated from healthy donors and those with gestational diabetes indicated that NOX4 downregulation in diabetic CB-ECFCs may directly inhibit SERPINE1 expression with consequent reduction in angiogenic capacity." (PMID 40457435, 2025).
glomerular disease (1 paper, 2020). "Collectively, these observations elucidate an important link between cellular HuR activation and signaling of TGFβ1, NF-κB, and Nox4 in glomerular disease." (PMID 32478392, 2020).
Glucose intolerance (1 paper, 2021). Glucose intolerance (GI) can be defined as dysglycemia that comprises both prediabetes and diabetes. "The specific role of NOX4 was also evidenced in high-fat diet-induced glucose intolerance in C57BL/6 mice using NOX4-selective inhibitor, GLX351322." (PMID 34943836, 2021).
granulosa cell tumor (1 paper, 2019). A slow-growing, malignant tumor, characterize by the presence of granulosa-like cells and Call-Exner bodies, that is almost always found in the ovary. "Recent studies showed that KGN cells, derived from a human granulosa cell tumor (GCT), express NADPH oxidase 4 (NOX4), an important source of H2O2." (PMID 31671815, 2019). "Although precise modes of action remain to be identified, involvement in GC proliferation has been suggested by studies employing the granulosa cell tumor (GCT) line KGN and a specific NOX4 blocker." (PMID 31671815, 2019).
Graves disease (1 paper, 2023). Graves' disease is an autoimmune disorder that leads to overactivity of the thyroid gland (hyperthyroidism).It is caused by an abnormal immune system response that causes the thyroid gland to produce too much thyroid hormones. "Graves’ disease also shows a high level of NOX4 protein, and this result can be explained by the constitutive activation of the TSH receptor (stimulating antibody, mutations) in Graves’ disease tissue." (PMID 37504283, 2023).
hemorrhage (1 paper, 2011). Loss of blood from the vascular compartment to the exterior or into nonvascular body space as a result of rupture or severance of the blood vessels. "In a latest study, Yu and co-workers have shown that ROS overproduction and NOX-4 increase in a trauma/hemorrhage rat model can be prevented and trauma-impaired endothelium-dependent vaso-relaxation restored through stimulation of HO-1 expression." (PMID 21906276, 2011).
hemorrhagic stroke (1 paper, 2023). A stroke caused by a bleed on the brain. "Genetic deletion or pharmacological inhibition of NOX2 and NOX4 reduces brain tissue damage and improves neurological outcomes following hemorrhagic stroke." (PMID 36793787, 2023).
hyperandrogenism (1 paper, 2025). Excessive secretion of androgens from the adrenal glands or gonads. "Conversely, hyperandrogenism itself amplifies ROS: excess androgens sensitize leukocytes and GCs to glucose, boost NOX4 activity, and trigger endoplasmic reticulum stress pathways that raise ROS levels." (PMID 40694958, 2025).
Hypoglycemia (1 paper, 2022). A decreased concentration of glucose in the blood. "In this study, changes in the levels of NOX2, NOX4, and 8-OHdG indicate that the release of ROS and mtDNA in model mice with hypoglycemia promoted pyroptosis." (PMID 35915611, 2022).